CCL1 (C-C motif chemokine ligand 1)
Diseases named in the same sentence as CCL1 in open-access papers (continued):
Sharing a sentence is not in itself a finding about the gene and the disease.
papilloma (1 paper, 2020). A benign epithelial neoplasm that projects above the surrounding epithelial surface and consists of villous or arborescent outgrowths of fibrovascular stroma. "Absence of CCL1 expression by iLCs in papillomas may be caused by the abundant functional Tregs in these lesions." (PMID 32210959, 2020). "Papilloma iLCs uniquely expressed IL-36γ at baseline and expressed CCL1 when cultured overnight outside their immunosuppressive microenvironment without additional stimulation." (PMID 32210959, 2020). "In contrast, iLCs from papillomas showed little, if any, CCL1 mRNA expression at baseline and very little increase after IL-36γ treatment." (PMID 32210959, 2020). "However, culturing these cells overnight outside of the immunosuppressive micromilieu present in papillomas releases these cells to express high levels of CCL1 mRNA." (PMID 32210959, 2020). "We now showed that baseline CCL1 expression by papilloma-derived iLCs is almost undetectable." (PMID 32210959, 2020). "Immature LCs from papillomas and foreskin did not express detectable CCL1 mRNA expression at baseline, and abdominal skin iLCs expressed extremely low levels of CCL1." (PMID 32210959, 2020). "Subsequent stimulation of papilloma iLCs with poly(I:C) or TNFα did not further increase their high level of CCL1 mRNA expression." (PMID 32210959, 2020). "Unlike CCL1, papilloma-derived iLCs expressed very high levels of CCL20 mRNA at baseline that did not further increase following IL-36γ stimulation (410 ± 65 and 422 ± 80, respectively)." (PMID 32210959, 2020). "We then asked whether expression of CCL1 and CCL20 mRNA by purified monocyte-derived iLCs from controls and patients differed from iLCs isolated from papilloma tissues." (PMID 32210959, 2020).
Pruritus (1 paper, 2025). Pruritus is an itch or a sensation that makes a person want to scratch. "These pathways include cytokines, such as IL-4, IL-13, IL-31, and TSLP, and chemokines, such as CCL1, CCL13, and CCL17, which have been implicated in barrier disruption, pruritus, and immune cell recruitment in AD." (PMID 41583462, 2025).
renal cell carcinoma (1 paper, 2015). "Studies have shown that MDSCs from patients with urothelial and renal cell carcinoma express CCR8 (the CCL1 receptor), and tumor-derived CCL1 promotes the accumulation of MDSCs in both the peripheral blood and tumor tissue." (PMID 26470881, 2015).
scleroderma (1 paper, 2020). Scleroderma is a rare autoimmune connective tissue disorder characterized by abnormal hardening of the skin and, sometimes, other organs. "We propose that the neutralization of CCL1 offers a potential means of preventing pulmonary complications induced by hMSCs when patients with Scl-GVHD or scleroderma are treated with hMSCs in the clinic." (PMID 32586381, 2020).
skin inflammation (1 paper, 2012). "IL-31 may enhance skin inflammation through the induction of several chemokine genes such as CCL17, CCL22 and CCL1 in human keratinocytes which subsequently leads to the recruitment of T-cells, and in turn may become new sources of IL-31." (PMID 22853438, 2012).
Splenomegaly (1 paper, 2015). Abnormal increased size of the spleen. "We observed a dramatic increase in the expression of several proinflammatory markers such as Il17a, Ifnγ, Tnfα, IL-1β and Ifitm1, and chemokines such as Ccl1, Cxcl10, Ccl22 and Xcl1, in ATMINΔLNBS1ΔL mice displaying splenomegaly, compared to the other genotypes." (PMID 26544571, 2015).
systemic lupus erythematosus (1 paper, 2022). An autoimmune multi-organ disease typically associated with vasculopathy and autoantibody production. "CCL1 and CCL2 promote basophil recruitment in skin lesions in patients with systemic lupus erythematosus." (PMID 36518763, 2022).
T-cell leukemia (1 paper, 2017). A malignant disease of the T-lymphocytes in the bone marrow, thymus, and/or blood. "Previous reports have indicated that CCL1 is overexpressed in adult T-cell leukemia cells, mediating an autocrine anti-apoptotic loop." (PMID 29202792, 2017).
viral meningitis (1 paper, 2019). Inflammation of the membranes surrounding the brain and spinal cord due to a viral infection. "Both, bacterial and viral meningitis additionally displayed significantly elevated concentrations of the cytokines CCL1, CCL19, CCL20, CXCL2, CXCL6, IFNγ, and IL16." (PMID 31727097, 2019).
virus infection (1 paper, 2010). "These differential responses (including transcripts encoding CCL1, CCL6, CXCL11, and CXCL12) not only vary minimally with age at inoculation, the differential responses themselves are minimal, demonstrating at most 2-fold induction in response to virus infection." (PMID 21078159, 2010).
ZIKV infection (1 paper, 2019). "ZIKV infection of HBMECs and RECs led to activation of several proinflammatory cytokines including IL-6, CCL1, and CCL5." (PMID 31249527, 2019).
tumor (105 papers, 2012 to 2025). "Histological analysis revealed that the number of CCL1‐positive cells, mainly tumour associated macrophages (TAMs) located in the stroma of CRC, decreased significantly at liver metastatic sites, while the expression level of CCR8 on CRC remained unchanged." (PMID 38506205, 2024). "Few M2b macrophages can be identified in early stage HCC; they increase in preponderance in parallel with increasing tumor stages, gradually overtaking the population of M1 cells, with M2b cells and the CCL1/CCR8 axis being linked." (PMID 39796695, 2024). "We also found that several of the downregulated genes including Ccl1, Ccl22, Cxcl13 or Ccr7 were associated with immunosuppression and decreased anti-tumour immunity." (PMID 37516803, 2023). "Chemokines were recently implicated in organ-specific metastasis of tumour cells, and human CCL1 is a potent monocyte chemoattractant that binds to and exclusively activates CCR8." (PMID 33484377, 2021). "CCL1 recruits tumor-associated macrophages and Tregs to the tumor niche." (PMID 38245792, 2024). "In addition, CCL1 has been shown to stimulate the chemotaxis of neutrophils and as such possesses angiogenic properties, implicated in tumor growth, migration and invasion in NSCLC." (PMID 34925341, 2021). "The observed levels of IL-23 and I-309 (also known as CCL1) in this study on treatment with free Doc in LNCaP cells correspond with their established pro-inflammatory roles and their role in promoting tumor growth and proliferation." (PMID 40507238, 2025). "To study the copper‐depleting dynamics in vivo, we monitored CCL‐1 bioluminescence in 4T1‐Luc tumor‐bearing mice after a single intravenous injection of TM@CD326hOMV." (PMID 40270472, 2025). "CCL1 also recruits a large number of Treg cells to the tumor site for immune suppression, promoting tumor growth." (PMID 39136031, 2024). "Further studies are warranted for identifying the association between CCL1 expression levels and the prognosis of CRC in terms of tumour location and developmental pathways such as ‘de novo’ carcinogenesis and serrated‐neoplasia sequences." (PMID 38506205, 2024). "Treg cells are mainly recruited to the tumor microenvironment by chemokines such as CCL1, CCL17, CCL22, CCL28, CXCL9, CXCL10, and CXCL11." (PMID 37686093, 2023). "Lastly, miR-126 regulates expression of SDF-1A and CCL1 genes which has a significant impact in reshaping tumor-infiltrating lymphocytes." (PMID 36499265, 2022). "Tumour cells themselves can attract eosinophils by producing CCL1 and stimulating eosinophils to secrete IL‐8 that facilitates eosinophil–cancer cell interaction leading to tumour cell death." (PMID 35344301, 2022). "Compared to virus-specific Th1 cells, this tumor-specific CD4+ T cell state differentially expressed genes associated with Th2 cells, including Igfbp7, Ccl1, Ccr8, and Il13, and downregulated Th1-associated genes, including Ccl5 and Ly6c2." (PMID 35829695, 2022). "Neutralizing of CCL-1 can be utilized as anti-tumor immunotherapy by suppressing the immunosuppressive activity of regulatory T cells." (PMID 36286030, 2022). "It was previously reported that M2 macrophages can induce Treg infiltration into the tumor microenvironment, inhibit T-cell immunity, and promote tumor growth by overexpressing CCL1 or CCL22." (PMID 35326602, 2022). "The activated Sp1high LECs promote transactivation of CCL1, facilitating the recruitment of TAMs and tumour cells and forming a positive feedback loop to strengthen the LVEM." (PMID 33484377, 2021). "CCL1 produced by LECs mediates TAM migration towards LECs during LVEM formation while also promoting tumour cell entry into LNs by increasing tumour cell motility." (PMID 33484377, 2021). "Patients with low PD-L1 levels displayed a strong trend towards an impaired prognosis, and circulating PD-L1 was negatively correlated with experimental markers of promalignant tumor characteristics such as CCL1, CCL21, CCL25 and CCL26." (PMID 34207359, 2021).
tumor (continued). "It was reported that the introduction of CCL1 induced tumor regression and resistance against tumors." (PMID 32214002, 2020). "In MDA-MB-231-resistant tumor-bearing mice, the content of TNFα in serum kept going up consistent with CCL1, a chemokine of M2b macrophage." (PMID 33214550, 2020). "Properties similar to this chemokine are also shown by viral macrophage inflammatory protein-I (vMIP-I) (homolog to CCL1)—a viral protein expressed in tumor cells transformed by the herpes virus." (PMID 33076281, 2020). "CCL1 production was significantly higher at advanced HCC stages (2.84 ± 3.49 ng/mL) compared to early tumor stages (0.03 ± 0.08 ng/mL)." (PMID 32824016, 2020). "In hepatocellular carcinomas, the expression of CCL1 is elevated in tumor stroma and peritumoral tissue." (PMID 33076281, 2020). "In this model, activation of CCR8 on tumor cells is mediated by CCL1 expressed on SCS endothelial cells in LNs allowing tumor cell entry from the collecting lymphatic vessel into the SCS." (PMID 32111837, 2020). "CC-type chemokine ligand 1 (CCL1) is expressed on the surface of LECs which bind CC-type chemokine receptor 8 (CCR8) on the surface of tumor cells and thus help in their trans-endothelial migration." (PMID 31921870, 2019). "The high percentage of TANs is a consequence of the secretion of chemoattractant chemokines (CCL1, 2, 5, and G-CSF) by tumor epithelial cells, that in turn recruit and activate TANs, strictly involved in tumor spread and metastasis." (PMID 31500143, 2019). "FAP+ CAFs modulate the tumor microenvironment through secretions such as C-C motif chemokine ligand 1, 2 and 5 (CCL1, CCL2, CCL5) and CXCL12 in HCC." (PMID 31540435, 2019). "The only macrophage subtype producing CCL1 is M2b which support vascularization and promote Th2‐biased tumour microenvironments." (PMID 28032353, 2017). "The circulating monocytic CD33highCD11b+ and granulocytic CD33lowCD11b+ myeloid cell subset as well as CD11b+ tumor infiltrating TAMs showed increased expression of the CCL1 chemokine receptor CCR8." (PMID 28197019, 2017). "CCL1 production and tumor cell migration to LECs are also promoted by proinflammatory mediators TNF, IL-1β and lipopolysaccharide." (PMID 28036019, 2016). "Whereas in tumor-bearing mice groups, most of cytokines were decreased after LF-MF exposure, including KC, CCL1, IFN-γ, CXCL9, CXCL12, TREM-1, CCL12, IL-1rα and IL-16." (PMID 24314291, 2013). "IgG4 reduces the expression of CD206, CD163, and CD14 on the surface of M2 macrophages, increases the production of CCL-1, IL-10, and IL-6, induces the M2b-like macrophage phenotype, which impairs the tumor cell phagocytosis function and the function of anti-cancer effector cells." (PMID 39758935, 2025). "CMTM4 regulates RTK function and further controls downstream signal activation, including NF-κB and Akt/mTOR pathways, which may induce tumor productions of various cytokines and chemokines in cancer cells, including CCL-1, IL-1β, G-CSF." (PMID 39948411, 2025). "CSC actively recruit Treg cells to the tumour microenvironment through the secretion of chemokines, such as CCL1, CCL2, and CCL5, a process that has been validated in a mouse glioblastoma model, in which CCL2 relies on the expression of CCR4 to mediate the Treg cell trafficking." (PMID 39184916, 2024). "Reduced CCL1 expression of TAMs at liver metastatic sites may partly explain the unique slow tumour progression of CRC, thus providing for a grace period for radical resection of metastatic lesions." (PMID 38506205, 2024). "Although CCL1 promotes tumor progression through Tregs, Tregs may also trigger the accumulation of CD8+ T cells." (PMID 38075694, 2023). "Furthermore, this strategy exploits activated T cell derived CCL1 to potentialize a positive feedback loop in CCR8+ cells recruitment to the tumor site." (PMID 35211124, 2022). "CCL-1 also has a prominent place in inflammation and apoptosis, angiogenesis, and tumor biology." (PMID 36286030, 2022).
tumor (continued). "Similarly, CCL1 and CCL2 have been shown to promote tumour metastasis by facilitating tumour‐associated macrophage recruitment." (PMID 36068649, 2022). "Here, miR‐3473b inhibitor significantly reduced the exosome‐mediated inflammatory genes including Il6, Ccl1, Ccl2, Ccl5 and Cxcl2 expression in fibroblasts, which suggest the potential role of exosomal miR‐3473b in establishing tumour‐promoting inflammation environment." (PMID 32449597, 2020). "Moreover, M2b secreted CCL1 are known to be Treg chemoattractant inducing suppression of host anti-tumor immunity." (PMID 33214550, 2020). "In the tumor, CCL1/I-309 expression occurs, among others, in CAF." (PMID 32781743, 2020). "In addition, CCL1 supports the immunosuppressive function of Treg in a tumor niche, which is crucial for the interaction of cancer stem cells and CAF with Treg." (PMID 33076281, 2020). "These PD1+ tumor-associated macrophages (TAMs) exhibited an M2-like surface profile, with a significant increase in the expression of CD206, IL-10, and CCL1, and a clear decrease in the expression of MHC class II, CD64, and IL-12 and the ability to phagocytose ovalbumin." (PMID 29799520, 2018). "Production of CCL17, CCL1, chemokine (C-X-C motif) ligand-13 (CXCL13) and CXCL8 (IL-8) has been shown to be associated with the activation program for M2 tumor associated macrophage (TAM), and is parts of mononuclear phagocyte-mediated regulatory circuits of innate and adaptive immunity." (PMID 26172457, 2015). "CCL1 plays a role not only in inflammation but also in apoptosis, angiogenesis and tumor biology." (PMID 22479563, 2012). "Specifically, tumor-associated macrophages (TAMs) create an immunosuppressive milieu through the production of a plethora of paracrine factors (IL-6, IL-12, TNF-alpha, TGF-beta, CCL1, CCL18) promoting the acquisition by CSCs of a stem-like, invasive and metastatic phenotype." (PMID 39981232, 2025). "CCL1 secretion is critical to maintain the M2b phenotype in mice and humans, while IL-10 has been found to impair the differentiation of infiltrated monocytes into mature dendritic cells (DCs), thereby compromising the competent host anti-tumor immune response." (PMID 39758935, 2025). "However, the expression of CCL1 is extremely low in a variety of tumour tissues." (PMID 37935468, 2024). "Consequently, CCL1 might be involved mainly in tumour progression through the AKT signalling pathway in Colo320DM cells." (PMID 38506205, 2024). "Chemokines including CXCL5/CXCR2 are essential for MDSC recruitment in 4T1 BALB/c murine tumor models, while CCL1, CCL2, CCL5, GM-CSF, and G-CSF facilitate MDSC expansion and aggregation in the tumor milieu." (PMID 40909271, 2025). "We further performed cytokine array analyses with tumor cells stimulated with EGF and found increased protein levels of G-CSF, GM-CSF, and CCL-1 in control cells compared to CMTM4 KD cells." (PMID 39948411, 2025). "Mechanistically, this immunosuppressive tumor microenvironment arises from N1-acetylspermidine efflux-dependent SRC signaling activation, which concurrently drives CCL1 macrophage polarization and CCR8 regulatory T-cell recruitment." (PMID 41293149, 2025). "In our study, we found that CMTM4 can modulate the tumor immune microenvironment by promoting EGFR recycling to increase G-CSF and CCL-1 production, which recruit neutrophils and MDSC to induce an immune suppressive tumor microenvironment." (PMID 39948411, 2025). "CCR8 is the only receptor of CCL1, so CCL1 activation of the CCR8 receptor on tumor cells promotes their proliferation and metastasis." (PMID 39136031, 2024). "In solid tumours, CCL1 is produced by TME‐composed cells such as TAMs, CAFs and regulatory T cells (Treg), and acts through CCR8 expressed in tumour cells, vascular endothelial cells and Treg." (PMID 38506205, 2024). "CCR8 is the sole receptor for CCL1, and the CCL1‐CCR8 axis promotes tumour activity in various malignancies." (PMID 38506205, 2024).